TRPC1 (transient receptor potential cation channel subfamily C member 1)
Diseases named in the same sentence as TRPC1 in open-access papers (continued):
Sharing a sentence is not in itself a finding about the gene and the disease.
tumor (continued). "The expression of TRPC1 is positively correlated with the tumor-node-metastasis staging and the depth of invasion in tumor patients." (PMID 39759147, 2024). "In previous studies, the high expression of TRPC1 promoted tumor cell growth and migration through the mechanisms of cytokinesis and chemotaxis, respectively." (PMID 35625048, 2022). "Subsequently, it was observed that TRPC1 protein was elevated in tumor tissue compared with normal endometrium (p < 0.001)." (PMID 35754147, 2022). "TRPC1 serves as a potential biomarker reflecting tumor features and long-term survival profile in patients with RCC." (PMID 35548183, 2022). "TRPC1 protein expression was up‐regulated in tumor tissue compared with normal endometrium of EC patients (IHC score: 5.4 ± 3.0 vs. 2.7 ± 1.7, p < 0.001)." (PMID 35754147, 2022). "A recent study investigated the TRPC1 expression in ccRCC tissue and demonstrated a positive correlation between the TRPC1-expression level and the tumor grade." (PMID 36613622, 2022). "Their tumor and paired adjacent tissue specimens were retrieved to assess TRPC1 mRNA expression using RT-qPCR and TRPC1 protein expression using immunohistochemistry (IHC)." (PMID 35548183, 2022). "In the present study, we demonstrate the role of the fluctuating acidic tumor microenvironment and TRPC1 in PDAC cell migration, proliferation, and cell cycle progression." (PMID 36230869, 2022). "In conclusion, we show for the first time that TRPC1 is upregulated in aggressive subtypes of PDAC patient tumor tissue and cell lines." (PMID 35887266, 2022). "Tumor TRPC1 mRNA high was related to shortened accumulating DFS (p = 0.038) and exhibited a correlating trend with declined OS (lacked statistical significance) (p = 0.162) in EC patients." (PMID 35754147, 2022). "Conclusively, TRPC1 expression elevates in tumor tissues, correlates with more advanced T stage, TNM stage, and unsatisfactory long-term OS in patients with RCC." (PMID 35548183, 2022). "In congruence with this, we show that TRPC1 is upregulated in PDAC tissue compared to non-tumor tissue samples." (PMID 35887266, 2022). "TRPC1 protein expression in tumor tissues and normal endometria of 176 resectable EC patients was determined using immunohistochemistry." (PMID 35754147, 2022). "Transient receptor potential channel 1 (TRPC1) facilitates the tumor growth, metastasis, and chemoresistance in a series of neoplasms, while its correlation with clinical features and survival profile in NSCLC patients remains elusive." (PMID 35106847, 2022). "At the cellular level, TRPC1 contributes to a plethora of physiological and pathophysiological processes, including tumor cell proliferation and growth." (PMID 35887266, 2022). "The results showed that TRPC1 mRNA expression was significantly upregulated in PDAC tissue samples compared to non-tumor tissue samples (N = 171 vs. 179, p < 0.01)." (PMID 35887266, 2022). "More importantly, TRPC1 acts as a tumor promoter by initiating tumor growth and metastasis as well as facilitating tumor chemoresistance." (PMID 35106847, 2022). "This indicates that the fluctuations in the acidic tumor microenvironment confer a more aggressive role to TRPC1." (PMID 36230869, 2022). "TRPC1 protein expression was up‐regulated in tumor tissue compared with normal endometrium (p < 0.001)." (PMID 35754147, 2022). "Contrarily, TRPC1 overexpression markedly facilitated tumor growth, concomitant with increased cell proliferation." (PMID 34642309, 2021). "Consistently, TRPC1 was highly expressed and distinctly colocalized with CaM and PI3K in the tumor tissues of AOM/DSS-induced WT mice, while the colocalization of CaM and PI3K was markedly receded in the tumor tissues of Trpc1-/- mice." (PMID 34642309, 2021). "Collectively, these findings demonstrate that TRPC1 plays an important oncogenic role in motivating tumor growth and tumorigenesis in vivo." (PMID 34642309, 2021).
tumor (continued). "TRPC1 was upregulated in CRC tissues compared with adjacent normal tissues and high expression of TRPC1 was associated with more aggressive tumor progression and poor overall survival." (PMID 34642309, 2021). "The abnormal expression of TRPC1 was found to be involved in tumor growth, migration, invasion, and differentiation." (PMID 33854967, 2021). "There was a striking increase in the mRNA levels of TRPC1 in the advanced stage (III/IV) compared with the early stage (I/II), suggesting that TRPC1 level increases during tumor progression." (PMID 34642309, 2021). "The TRPC1 knockdown group demonstrated a smaller mean tumor volume and weight than the control cells and the inhibited rate was 77.2%." (PMID 34642309, 2021). "Collectively, TRPC1 functions as a versatile oncogene in CRC by promoting tumor genesis, growth, and metastasis." (PMID 34642309, 2021). "The abnormal expression of TRPC1 can accelerate the uncontrolled proliferation and invasion of tumor cells." (PMID 33854967, 2021). "Compared with the vector group, the overexpression of TRPC1 resulted in a greater lung metastasis burden (200% tumor incidence of control)." (PMID 34642309, 2021). "Our study shows that GSC from patient-derived surgical tumor specimen express Orai1 and TRPC1 as well as STIM1, as do the adult neural stem cells from which GSC originate, at least in part." (PMID 34298643, 2021). "Taken together, these results provide evidence that TRPC1 plays a pivotal oncogenic role in colorectal tumorigenesis and tumor progression by activating CaM-mediated PI3K/AKT signaling axis." (PMID 34642309, 2021). "In the CAM xenograft model, DOX and PEMF exposure also synergistically reduced tumor size as well as reduced Transient Receptor Potential Canonical 1 (TRPC1) channel expression." (PMID 35141145, 2021). "Collectively, these data suggest that TRPC1 induces cell invasion and migration in vitro and tumor metastasis in vivo." (PMID 34642309, 2021). "Mice with inducible knockdown of TRPC1 had a shallow, significantly smaller tumor size compared to wild-type TRPC1 expression." (PMID 32046188, 2020). "Taken together, TRPCs, especially TRPC1, play essential roles in modulation of tumor progression and osteoclast activation." (PMID 32211326, 2020). "Patients with M0 stage tumors showed only CACNA1H, SLC24A3 and NALCN associated with OS differences, while ATP2A1, ATP13A2, TRPC1, and NALCN proved to be significantly associated with OS in the N1–N3 tumor stage patient subgroup." (PMID 31083561, 2019). "In this view, Stim1, Orai1, and TRPC1 stand out as very promising molecular identities to hit to adverse tumor neovascularization." (PMID 23049731, 2012). "The ability of PEMFs to activate TRPC1 residing on TAMs may hence be exploited to enhance their loading with DOX to decisively polarize them into the anti-tumor state." (PMID 39594815, 2024). "As a result, TRPC1 was up‐regulated in tumor tissue than that in normal endometrium of EC patients." (PMID 35754147, 2022). "Possible explanation could be that TRPC1 not only induces the proliferation, migration, and metastasis of tumor cell, but also enhances the chemoresistance in several types of tumors, which might contribute to a higher relapse risk for surgical NSCLC patients." (PMID 35106847, 2022). "TRPC1 IHC stain examples in normal endometrium and tumor tissue of EC patients were exhibited." (PMID 35754147, 2022). "The authors postulated that TRPC1 might enhance cell proliferation via Ca2+ entry and Ca2+-NFATc3 signaling pathways leading to ccRCC growth which is concomitant with higher tumor grading." (PMID 36613622, 2022). "However, the interplay between the acidic tumor microenvironment and TRPC1 expression and downstream mechanisms contributing to PDAC progression are unexplored." (PMID 36230869, 2022).
tumor (continued). "After analysis, the TRPC1 IHC score was increased in the tumor tissue compared with the adjacent tissue (5 ± 2.9 vs. 2.9 ± 1.9, P < 0.001); TRPC1 mRNA expression was higher in the tumor tissue than in the adjacent tissue (2.642 (1.652–3.367) vs. 1 (0.643–1.347), P < 0.001)." (PMID 35548183, 2022). "High (vs. low) TRPC1 protein in the tumor was associated with shorter OS (P = 0.017), while high (vs. low) TRPC1 mRNA in the tumor was not correlated with OS (P = 0.144)." (PMID 35548183, 2022). "In addition, TRPC1 mRNA expression and TRPC1 IHC score were closely correlated with each other in tumor and adjacent tissues, respectively (both P < 0.001)." (PMID 35548183, 2022). "Correspondingly, TRPC1 facilitates the tumor cell migration or metastasis." (PMID 35106847, 2022). "Besides, the 3-, 5-, and 7-year overall survival (OS) were 81.4, 68.6, and 60.2%, respectively in patients with high tumor TRPC1 protein, while they were 89.3, 82.7, and 76.7%, respectively in patients with low tumor TRPC1 protein." (PMID 35548183, 2022). "Hence, we investigated the effect of the acidic tumor microenvironment on the expression and the localization of TRPC1 in PANC-1 cells." (PMID 36230869, 2022). "Possible explanations could be that: according to the evidences above, TRPC1 induces the proliferation, migration, and metastasis of tumor cell." (PMID 35106847, 2022). "Similarly, in this study, both TRPC1 protein and mRNA expressions were increased in tumor tissue compared with normal endometrium of EC patients." (PMID 35754147, 2022). "Hence, TRPC1 has the independent pleiotropic promoting effects on the genesis, tumor growth, and metastasis of CRC." (PMID 34642309, 2021). "Our previous work revealed that the expression pattern of TRPC1 may differ between different tumors or in different pathological stages of the same tumor." (PMID 33854967, 2021). "Especially TRPV2 and TRPC1 mRNA expression could serve as potential biomarkers for tumor invasiveness." (PMID 34936030, 2021). "TRPC1 may play a significant role as a tumor suppressor gene, and is expected to become a new prognostic factor to guide the clinical diagnosis and treatment of ESCC." (PMID 33854967, 2021). "The expression of TRPC1 had been extensively studied in various types of tissue or tumor." (PMID 33854967, 2021). "Consistent with the increased TRPC1 mRNA, TRPC1 protein expression also markedly increased 1.26-fold and 1.41-fold in tumor tissues compared with adjacent normal tissues in both individual CRC samples (n = 98) and additional 13 pairs of samples in the local cohort." (PMID 34642309, 2021). "We initially hypothesized that, in the emergence and progression of ESCC, TRPC1 may be related to tumor growth, invasion, and metastasis." (PMID 33854967, 2021). "Moreover, H&E-stained lung sections revealed that TRPC1-overexpressed tumors showed extensive tumor tuberous tissues, which is consistent with the increased cell proliferation in metastases lung tissues." (PMID 34642309, 2021). "In line herewith, increased TRPV2 and TRPC1 mRNA expression levels were observed in both primary and metastatic EC biopsies and in primary EC cells with a high EMT status, indicating an association with an aggressive tumor phenotype." (PMID 34936030, 2021). "We also found two other significant genes—MCOLN2 and TRPC1—in tumor stage III patients." (PMID 31083561, 2019). "This study also showed that shRNA suppression of TRPC1 in a flank tumor model, reduced tumor size." (PMID 30691160, 2019). "Finally, we discuss the role of endothelial TRP channels in aberrant tumor vascularization by focusing on TRPC1, TRPC3, TRPV2, TRPV4, TRPM8, and TRPA1." (PMID 32038296, 2019). "Of note, HIF-1 has been shown to control also TRPC1 expression, although it is still unclear whether this regulation also occurs in tumor microenvironment and, if so, why TRPC1 is up-regulated in RCC-ECFCs, but not in RCC-ECFCs." (PMID 29324706, 2018).
tumor (continued). "There are also a few reports describing TRPC1 expression in tumors and tumor cells raising the possibility that this protein may serve as a diagnostic marker." (PMID 25268281, 2014). "Thus, TRPC1 exerts a more aggressive role after adaptation to the acidic tumor microenvironment." (PMID 36230869, 2022). "Similar to RCC-ECFCs, however, the pharmacological inhibition of SOCE abrogated BC-ECFC proliferation and tube formation, thereby confirming that Orai1 and TRPC1 could serve as reliable targets to interfere with tumor vascularization, although this hypothesis remains to be validated in vivo." (PMID 29324706, 2018). "An increased expression of TRPC1 is has been positively correlated with epithelial–mesenchymal transition (EMT), a complex process that induces tumor cells to spread and fight apoptosis, thus conferring a more aggressive phenotype." (PMID 37892239, 2023). "Additionally, TRPC1 mRNA and protein expressions were not linked with tumor markers (all p > 0.05)." (PMID 35106847, 2022). "High expression of TRPM4 and TRPM7 was detected in primary tumor biopsies, while TRPV4, TRPC4, TRPC6 and especially TRPV6 expression was limited, while the expression of TRPC1 and TRPV2 are moderately expressed." (PMID 34936030, 2021). "Our study firstly discovered that Trpc1 knockout significantly reduced the tumor incidence rate in CRC mice model, suggesting that TRPC1 plays an incitant role in the genesis of CRC." (PMID 34642309, 2021). "While TRPV2 mRNA expression is mainly correlated to stage and invasion status of the cell, i.e., expression of MMPs, TRPC1 mRNA expression is increased in all cell lines that underwent EMT, regardless the tumor stage or MMP expression." (PMID 34936030, 2021). "Intriguingly, the immunofluorescence analysis demonstrated that TRPC1, CaM, and PI3K were highly colocalized in the cytoplasm of CRC cells, which was further verified in human CRC tumor tissues and adjacent tissues." (PMID 34642309, 2021). "The present study is the first of its kind to reveal that TRPC1, CaM, and PI3K were co-located in CRC cells and tumor tissues using immunofluorescence." (PMID 34642309, 2021). "We argue that the functional interplay between Piezo1, TRPV4 and TRPC1 might have a pathophysiological relevance in PDAC and other tumor entities." (PMID 40019468, 2025). "Thus, we compared the TRPC1 expression and localization in human PDAC and adjacent non-tumor tissue samples from our local cohort (N = 21)." (PMID 35887266, 2022). "In addition, transcriptomic analysis of glioblastoma tumor tissues showed overexpression of STIM1, ORAI1, and TRPC1." (PMID 35711942, 2022). "Therefore, we analyzed the expression of TRPC1 in normal pancreatic tissue and human PDAC samples using the PAAD TCGA dataset of normal and tumor samples." (PMID 35887266, 2022). "In this study, we detected the TRPC1 protein expression by immunohistochemistry (IHC) and the TRPC1 mRNA expression by RT-qPCR in the RCC tissue and adjacent tissue, and subsequently investigated their linkages with tumor features and prognosis in patients with RCC." (PMID 35548183, 2022). "Moreover, high levels of TRPC1 positively correlated with TNM stage and tumor metastases in CRC patients." (PMID 34642309, 2021). "Furthermore, the overexpression of TRPC1 has been discovered to be correlated with small tumors low proliferating (Grade 1), whereas TRPV4 is correlated with tumor grade, tumor size, and patient overall survival." (PMID 34209733, 2021). "Overall, our results indicated that high levels of NALCN, TRPC1, TRPV2, and CACNA1H could be suggestive of an advanced stage tumor." (PMID 31083561, 2019). "Moreover, the expression of TRPC1, ORAI1, ORAI2, ORAI3 and STIM1 was increased in tumor cells in contrary to STIM2 protein which was found to be depleted." (PMID 31010205, 2019).
tumor (continued). "Moreover, TRPC1 was considerably more localized to the plasma membrane in tumor cells when compared to non-tumor cells, where TRPC1 was found mainly expressed in the cytoplasm (p < 0.0001)." (PMID 35887266, 2022). "TRPC1 also localizes to the plasma membrane of tumor cells when compared to non-tumor cells." (PMID 35887266, 2022). "Consistent with the increased TRPC1 mRNA expression, TRPC1 protein expression also significantly increased in human PDAC samples, where TRPC1 localizes to the plasma membrane, compared to adjacent non-tumor tissue, where it localizes in the cytoplasmic compartments." (PMID 35887266, 2022). "The explanation for our findings was that TRPC1 might promote proliferation via Ca2+ entry and Ca2+- nuclear factor of activated T cells, cytoplasmic 3 (Ca2+-NFATc3) signaling pathways, thus resulting in the RCC growth and subsequently affecting tumor size." (PMID 35548183, 2022). "By analyzing the GSE62254 dataset, we found a significant association of prognostic CaRG expression with tumor stages for TRPC1, CACNA1H, and TRPM7, while no genes resulted in being significantly associated with tumor stages from the analysis of the GSE15460 dataset." (PMID 31083561, 2019). "Collectively, these findings suggest that TRPC1 is upregulated in human PDAC tissue and cell lines when compared to adjacent non-tumor tissue and a non-cancerous cell line." (PMID 35887266, 2022). "As VEGF failed to induce pro-angiogenic Ca2+ oscillations in tumor-derived ECFCs, a feature which might underpin the primary and secondary resistance to anti-VEGF drugs, TRPC1 (and SOCE) inhibition could represent a promising strategy to interfere with tumor vascularization." (PMID 32038296, 2019).
bacterial infection (5 papers, 2016 to 2025). "Through the TLR4/TRPC1/NF-κB signaling pathway, TRPC1 has also been shown to contribute to the inflammatory response to bacterial infection." (PMID 40533673, 2025). "TRPC1 plays an important role in the protection from bacterial infection, through TLR4-TRPC1 activation of protein kinase (PK) Cα pathway." (PMID 29928281, 2018).
cardiovascular diseases (5 papers, 2014 to 2023). "Such a finding provides novel insights into the role of the IKCa and TRPC1 channels in VSMC proliferation and the pathogenesis of related cardiovascular diseases." (PMID 36562293, 2023).
infection (3 papers, 2016 to 2025). The state of being infected such as from the introduction of a foreign agent such as serum, vaccine, antigenic substance or organism. "TRPC-1 allows the entry of Ca2+ inside the macrophage, which leads to an intense inflammatory response and increases infection susceptibility as compared to the TRPC-1-deficient cells." (PMID 37139494, 2023). "Upon infection, TRPC1 (−/−) mice exhibited decreased survival, severe lung injury, and systemic bacterial dissemination." (PMID 26482920, 2016). "Additionally, genes involved in calcium signaling and ion channel regulation—PKD1, PKHD1, TRPC1, TRPM6, and TRPM7—highlight the importance of cellular homeostasis and signaling during infection." (PMID 41114509, 2025).
metabolic disorders (3 papers, 2017 to 2025). "Collectively, these results provide a robust experimental rationale for targeting TRPC1 in the therapeutic development of metabolic disorders." (PMID 40568618, 2025). "In summary, this work provides novel insights into the role of vascular endothelial cells in metabolic diseases and identifies TRPC1 as a highly valuable therapeutic target for intervention." (PMID 40568618, 2025).
neurodegenerative disease (3 papers, 2018 to 2024). A disorder of the central nervous system characterized by gradual and progressive loss of neural tissue and neurologic function. "In addition, TRPC1 knockout mice (TRPC1−/−) exhibited loss of dopaminergic neurons in substantia nigra, which occurs in the pathogenesis of neurodegenerative diseases." (PMID 29615894, 2018). "Therefore, the various pathological models demonstrated the opposite effects of TRPC1 and TRPC5 in neurodegenerative diseases and neurite outgrowth." (PMID 39000357, 2024).